MIR29A (microRNA 29a)
Synonyms: hsa-mir-29; hsa-mir-29a; MIRN29; MIRN29A; miRNA29A; mir-29a
Gene: MicroRNA gene on chromosome 7 (130,876,747 to 130,876,810, reverse strand). Ensembl gene ENSG00000284032.
Gene Ontology:
Biological process: miRNA-mediated post-transcriptional gene silencing
Cellular component: RISC complex
Homologues: Orthologues: chimpanzee ptr-mir-29a (100% identical), guinea pig MIR29A (100% identical), macaque MIR29A (100% identical), pig ssc-mir-29a (100% identical), mouse Mir29a (98% identical), rabbit MIR29A (98% identical), tropical clawed frog xtr-mir-29a (84% identical), zebrafish mir29a-1 (80% identical). Paralogues in human: MIR29C (80% identical), MIR29B1 (70% identical), MIR29B2 (67% identical).
Diseases named in the same sentence as MIR29A in open-access papers:
MIR29A is named in the same sentence as 4 diseases in open-access papers, as found by Europe PMC text mining. Sharing a sentence is not in itself a finding about the gene and the disease. The quoted sentences say what the papers report.
liver fibrosis (1 paper, 2019). "Mir29a and lipid-related genes were up-regulated after the recovery of CCl4-induced liver fibrosis in mice." (PMID 30781750, 2019). "Overexpressing Mir29a/b markedly reduced the degree of liver fibrosis induced by CCl4 in mice and decreased Collagen expression in LX-2 cells." (PMID 30781750, 2019). "Collectively, MIR29a plays an important role during the trans-differentiation of aHSCs in the resolution of liver fibrosis, in part, through regulation of ATP6V1C1." (PMID 30781750, 2019). "The expression of Atp6v1c1 was negatively correlated with Mir29a in CCl4-induced liver fibrosis in mice as well as in human HSC in vitro." (PMID 30781750, 2019). "MIR29a plays an important role during the resolution of liver fibrosis, which may be through the regulation of ATP6V1C1." (PMID 30781750, 2019). "We propose a new mechanism of action of MIR29a in the resolution of liver fibrosis." (PMID 30781750, 2019). "Thus, ATP6V1C1 may be regulated by MIR29a and promote the fibrogenesis while inhibiting the lipogenesis progress during liver fibrosis." (PMID 30781750, 2019).
cancer (1 paper, 2021). A tumor composed of atypical neoplastic, often pleomorphic cells that invade other tissues. "In addition, serum MIR29A expression normalized to MIR16 in HCC patients and non-cancer individuals from the Gene Expression Omnibus (GEO) dataset presented a similar trending (p < 0.001)." (PMID 34206143, 2021).
MIR29A also shares sentences with these, for which no sentence is quoted: tumor (2 papers); breast carcinoma (1).